ZKSCAN4 (zinc finger with KRAB and SCAN domains 4)
Description:
May be involved in the transcriptional activation of MDM2 and EP300 genes.
Synonyms: ZNF307; ZNF427; p373c6.1; P1P373C6; FLJ32136; ZSCAN36
Tractability: PROTAC: UniProt records ubiquitination sites on it; ubiquitination databases record sites on it.
Gene: Protein-coding gene on chromosome 6 (28,241,697 to 28,252,924, reverse strand). Ensembl gene ENSG00000187626.
Subcellular location: Nucleus
Subcellular location (Human Protein Atlas): Nucleoplasm
Pathways (Reactome):
Gene expression (Transcription): Generic Transcription Pathway
Gene Ontology:
Molecular function: identical protein binding; protein binding; DNA-binding transcription factor activity, RNA polymerase II-specific; RNA polymerase II cis-regulatory region sequence-specific DNA binding
Biological process: regulation of transcription by RNA polymerase II; regulation of DNA-templated transcription
Cellular component: nucleoplasm; nucleus
Genetic constraint (gnomAD): Loss-of-function variants: 28 observed, 36.98 expected, observed/expected ratio (o/e) 0.76, 90% interval 0.56 to 1.04. The synonymous counts are far from expectation, so gnomAD's model fits this gene poorly and the ratio says little. Missense variants: 556 observed, 685.01 expected, observed/expected ratio (o/e) 0.81, 90% interval 0.76 to 0.87. Synonymous variants: 208 observed, 259.79 expected, observed/expected ratio (o/e) 0.8, 90% interval 0.71 to 0.9.
Homologues: Orthologues: chimpanzee ZKSCAN4 (99% identical), macaque ZKSCAN4 (96% identical), pig ZKSCAN4 (83% identical), dog ZKSCAN4 (75% identical), rat Zkscan3 (71% identical), mouse Zkscan3 (70% identical), mouse Zkscan4 (65% identical), rat Zkscan4 (65% identical). Paralogues in human: ZKSCAN3 (84% identical), ZKSCAN8 (43% identical), ZKSCAN1 (41% identical), ZSCAN12 (40% identical), ZSCAN21 (40% identical), ZSCAN30 (39% identical), ZNF397 (38% identical), ZSCAN26 (38% identical), ZSCAN22 (37% identical), ZNF165 (36% identical), ZNF263 (35% identical), ZNF394 (35% identical), and 18 more.
Diseases named in the same sentence as ZKSCAN4 in open-access papers:
ZKSCAN4 is named in the same sentence as 12 diseases in open-access papers, as found by Europe PMC text mining. Sharing a sentence is not in itself a finding about the gene and the disease. The quoted sentences say what the papers report.
schizophrenia (3 papers, 2013 to 2020). A major psychotic disorder characterized by abnormalities in the perception or expression of reality. "Several ZKSCAN4 polymorphisms were strongly associated with schizophrenia in the Chinese Han population, although underlying molecular mechanisms are not known." (PMID 32117005, 2020). "Systematic meta-analysis on the psychotic diseases including schizophrenia, BAD, and ADHD identified several gene variants in ZNF804A, the zinc finger DHHC-type-containing 8 (ZDHHC8) and the zinc finger with KRAB and SCAN domain 4 (ZKSCAN4) genes." (PMID 32117005, 2020). "Additionally, our earlier two-stage GWAS also found that three single-nucleotide polymorphisms (SNPs; i.e., rs1233710 in ZKSCAN4, rs1635 in NKAPL, and rs2142731 in PGBD1) within this locus had a strong association with schizophrenia in a Chinese Han population." (PMID 23437227, 2013).
hepatocellular carcinoma (2 papers, 2021 to 2025). A malignant tumor that arises from hepatocytes. "Researchers have shown that ZKSCAN4 reduces cell proliferation, migration, and invasion in a hepatocellular carcinoma model." (PMID 41149858, 2025).
epilepsy (1 paper, 2026). A brain disorder characterized by episodes of abnormally increased neuronal discharge resulting in transient episodes of sensory or motor neurological dysfunction, or psychic dysfunction. "Nine shared genetic loci and six pleiotropic genes, including SCN1A, PGBD1, ZKSCAN3, ZKSCAN4, VRK2, and ZSCAN23, have been identified between epilepsy and psychiatric disorders." (PMID 41733899, 2026).
hypothyroidism (1 paper, 2024). Abnormally low levels of thyroid hormone. "We found that the 6p22.1 locus and genes, including ZKSCAN4 and MAPT, may play important roles in hypothyroidism and psychiatric disorders." (PMID 38904036, 2024).
cancer (2 papers, 2024 to 2025). A tumor composed of atypical neoplastic, often pleomorphic cells that invade other tissues. "Again, selective upregulation of transcriptional and epigenetic regulators in responders is evident; examples include PRDM5, ZNF230, ZCCHC9, ZKSCAN4, and the epigenetic regulator ALKBH3, which demethylates DNA and RNA in cancer cells." (PMID 39450169, 2024).
psychiatric disorder (2 papers, 2024 to 2026). A disorder characterized by behavioral and/or psychological abnormalities, often accompanied by physical symptoms. "Polymorphisms of zinc finger 4 (ZKSCAN4) with KRAB and SCAN structural domains located on chromosome 6p21-p22.1 were strongly associated with psychiatric disorders." (PMID 38904036, 2024).
ZKSCAN4 also shares sentences with these, for which no sentence is quoted: cardiac hypertrophy (1 paper); cognitive deficit (1); COVID-19 (1); prostate carcinoma (1); rheumatoid arthritis (1); tumor (1).